ALOX15B (arachidonate 15-lipoxygenase type B)
Diseases named in the same sentence as ALOX15B in open-access papers (continued):
Sharing a sentence is not in itself a finding about the gene and the disease.
tumor (31 papers, 2012 to 2026). "Functioning as in a tumor suppressor mode in the prostate, the alternatively spliced variants of ALOX15B are found to induce cell-cycle arrest and senescence in the epithelial cells of the normal human prostate." (PMID 38612771, 2024). "Treatment with the HDAC inhibitor tucidinostat restored ALOX15B expression, enhanced tumor cell apoptosis, reinstated antigen presentation, and reprogrammed the tumor immune landscape in both cell lines and in vivo models." (PMID 41527135, 2026). "CONCLUSIONS: ALOX15B is a key epigenetically regulated gene in DLBCL that modulates the tumor immune microenvironment and response to chemotherapy." (PMID 41527135, 2026). "Compared to 8 tumor‐adjacent normal pancreatic tissues, ALOX15B expression remained higher in KRASwt‐PDAC tissues but was considerably reduced in KRASmut‐PDAC tissues." (PMID 40569151, 2025). "Platelet-type ALOX12 and ALOX5 have been widely studied to induce carcinogenesis while ALOX15 and ALOX15B exhibit anti-carcinogenic activities although several studies demonstrate dual roles in regulating tumor development." (PMID 38612771, 2024). "ALOX15 and ALOX15B on the other hand majorly exhibit anti-carcinogenic properties, even though various studies demonstrate their dual roles in regulating tumor development." (PMID 38612771, 2024). "Since ALOX15B is expressed at high levels in human prostate and since enzyme expression is downregulated in prostate cancer, a tumor suppressor role of the enzyme has been suggested." (PMID 39596127, 2024). "Five tumor antigens, including ALOX15B, HS3ST2, PIGR, ZMYND15 and LIMK1, were identified for PRCC, which were correlated with patients’ prognoses and infiltration levels of APCs." (PMID 36836593, 2023). "Taken together, five tumor antigens (ALOX15B, HS3ST2, PIGR, ZMYND15, and LIMK1), with potentially provocative effects on immunological functions, were identified and considered as eligible candidates for anti-PRCC mRNA vaccine development." (PMID 36836593, 2023). "After that, five tumor antigens (ALOX15B, HS3ST2, PIGR, ZMYND15, and LIMK1) were identified to be candidates for the mRNA-based vaccine development, all of which were correlated with survival time of PRCC patients and the degree of APC infiltration." (PMID 36836593, 2023). "Collectively these alterations in signaling pathways suggests a role for 15-HETE produced by ALOX15B as a tumor suppressor through reducing cellular proliferation, promoting apoptosis and enhancing cytokine secretion." (PMID 36438817, 2022). "Studies in carcinoma cell lines reveal more insight into the role of ALOX15B as a tumor suppressor in cancer through cellular signaling pathways." (PMID 36438817, 2022). "This analysis identified three genes expressed in tumor cells, i.e. ALOX15B, the leukotriene B4 receptor gene LTB4R2 and the PGE2 receptor gene PTGER3." (PMID 27215396, 2016). "Silencing ALOX15B promoted tumor cell proliferation and resistance to doxorubicin." (PMID 41527135, 2026). "While the role of ALOX15 and ALOX15B in tumor-associated macrophages (TAMs) is not yet fully understood, numerous ALOX15/B metabolites, particularly resolvins and lipoxins, exhibit anti-tumorigenic properties." (PMID 38612771, 2024). "A similar tumor-suppressor effect of human ALOX15B was suggested for breast cancer." (PMID 39596127, 2024). "Whereas in vitro experiments pointed to reduced cellular proliferation, migration and cell cycle progression along with increased apoptosis, hyperplasia in vivo is accompanied by attenuated tumor formation, and both in vitro and in vivo experiments link ALOX15B expression with senescence." (PMID 36438817, 2022). "Arachidonate 15-lipoxygenase, type B (ALOX15B) upregulated in RCC-infiltrating macrophages, mediates lipid metabolism in TAMs and contributes to tumor progression as well as tumor immunity." (PMID 37221577, 2023).
tumor (continued). "Herein, we found that 5 genes (Shisa3, PADI1, LRP2, ANGPTL4 and ALOX15B) were upregulated and 4 genes (CXCL9, ADAMDEC1, SCGB1A1/CC10, HLA-G) were downregulated in PR tumor tissues compared to SD tumor tissues." (PMID 31801598, 2019). "As shown by IHC staining, the expressions of ALOX15 and ALOX15B were strikingly down-regulated, while ALOX5 and ALOX12 were strikingly up-regulated in tumor, compared with those in surrounding tissue." (PMID 31528237, 2019). "In addition, ALOX15B, LCN2, PRSS12, CD79B and ITSN2 showed tumor lesion-specific changes for all four patients." (PMID 37488117, 2023). "Multiple tumor suppressor genes like PHF23, EIF5A, KCTD11, MAP2K4 and ALOX15B, have been reported to promote tumorigenesis when lost, indicating that gene expression regulation, signal transduction, arachidonate lipoxygenase and other cellular pathways are altered with the loss of chromosome 17p." (PMID 36750552, 2023). "However, ALOX15B is downregulated or completely absent in more than 70% of PCa cases, exerting a tumor suppressive function." (PMID 34490029, 2021).
cancer (13 papers, 2014 to 2025). A tumor composed of atypical neoplastic, often pleomorphic cells that invade other tissues. "The AA metabolism alteration with the lipoxygenase-cyclooxygenase pathway unbalances implied that a gain of vulnerability for cancers with del(17p) or ALOX15B loss." (PMID 36750552, 2023). "Given that dysregulation in steroidogenesis is associated with cancer and other diseases, distinct and cell specific alterations in ALOX15B expression have been linked to various pathologies." (PMID 36438817, 2022). "Therefore, our results present here uncovered a novel mechanism underlying ALOX15B downregulation in cancer." (PMID 40569151, 2025). "The major enriched pathways included Arachidonic acid metabolism, Steroid hormone biosynthesis, Pathway in cancer, etc, and the major functional genes included the alox15b, gng7, hif1a, ppara, and pla2g." (PMID 41462646, 2025). "With this review, we aim to summarize the existing findings on the enzymatic and biological function of ALOX15B and cast light on its implication in inflammatory diseases and cancer." (PMID 36438817, 2022). "It is therefore possible that an increase in ALOX15B expression occurs in both in carcinoma cells derived from ovarian tissue along with TAMs." (PMID 36438817, 2022). "Like in inflammation, the role of ALOX15B in cancer is inconclusive." (PMID 36438817, 2022). "However, the metabolic mechanism in cancer cells with del(17p) or ALOX15B loss has not been well understood." (PMID 36750552, 2023). "Our present results proved that KRASmut/ABHD17C axis–mediated ALOX15B downregulation was functionally and clinically relevant to KRAS‐mutant cancer pathogenesis." (PMID 40569151, 2025). "Endocrine system development and cancer growth-related ceRNA regulation are found in TNBC; HOXA5, SCAPER, PAK6, PBX1, PITX1, and ALOX15B are the relevant genes involved; and hsa-miR-296-5p, hsa-miR-185-5p, hsa-miR-7851-3p, hsa-miR-3187-3p, and hsa-miR-10396b-5p are the relevant miRNAs involved." (PMID 37483500, 2023).
infection (1 paper, 2022). The state of being infected such as from the introduction of a foreign agent such as serum, vaccine, antigenic substance or organism. "The observation that Alox15b-/- mice need more time to recover from an experimental infection with the influenza virus suggests that Alox15b may play a role for the normal functionality of the immune system." (PMID 35740398, 2022).
ALOX15B also shares sentences with these, for which no sentence is quoted: neurological disorders (2 papers); prostate intraepithelial neoplasia (2); pulmonary artery hypertension (2); renal cell carcinoma (2); acute myeloid leukemia (1); adenocarcinoma (1); amaurosis fugax (1); autosomal recessive congenital ichthyosis (1); cerebral infarction (1); Cerebral ischemia (1); cervical cancer (1); COVID-19 (1); diffuse large B-cell lymphoma (1); edema (1); gastric cancer (1); inflammatory skin disease (1); kidney cancer (1); leukemia (1); lung squamous cell carcinoma (1); multiple sclerosis (1); neuroendocrine tumors (1); non-small cell lung carcinoma (1); ovarian tumors (1); pulmonary hypertension (1); type 1 diabetes (1).